AGO1 (argonaute RISC component 1)
Description:
Required for RNA-mediated gene silencing (RNAi). Binds to short RNAs such as microRNAs (miRNAs) or short interfering RNAs (siRNAs), and represses the translation of mRNAs which are complementary to them. Lacks endonuclease activity and does not appear to cleave target mRNAs. Also required for transcriptional gene silencing (TGS) of promoter regions which are complementary to bound short antigene RNAs (agRNAs).
Synonyms: hAgo1; EIF2C1; EIF2C; GERP95; NEDLBAS; Q99
Tractability: PROTAC: UniProt records ubiquitination sites on it; ubiquitination databases record sites on it; its protein half-life has been measured.
Gene: Protein-coding gene on chromosome 1 (35,869,808 to 35,930,532, forward strand). Ensembl gene ENSG00000092847.
Subcellular location: Cytoplasm, P-body
Subcellular location (Human Protein Atlas): Cytoplasmic bodies; Cytosol
Pathways (Reactome):
Gene expression (Transcription): MicroRNA (miRNA) biogenesis; Post-transcriptional silencing by small RNAs; RUNX1 regulates genes involved in megakaryocyte differentiation and platelet function; Regulation of NPAS4 mRNA translation; Regulation of RUNX1 Expression and Activity; Small interfering RNA (siRNA) biogenesis; Transcriptional Regulation by VENTX; Transcriptional regulation by small RNAs
Signal Transduction: Ca2+ pathway; Competing endogenous RNAs (ceRNAs) regulate PTEN translation; Estrogen-dependent gene expression; MAPK6/MAPK4 signaling; MTOR signalling; NR1H3 & NR1H2 regulate gene expression linked to cholesterol transport and efflux; Pre-NOTCH Transcription and Translation; Regulation of PTEN mRNA translation; TGFBR3 expression
Cell-Cell communication: Regulation of CDH1 mRNA translation by microRNAs; Regulation of CDH11 mRNA translation by microRNAs
Cellular responses to stimuli: Oncogene Induced Senescence; Oxidative Stress Induced Senescence
Developmental Biology: Regulation of MITF-M-dependent genes involved in apoptosis
Disease: Nuclear events stimulated by ALK signaling in cancer
Immune System: Regulation of PD-L1(CD274) translation
Gene Ontology:
Molecular function: core promoter sequence-specific DNA binding; double-stranded RNA binding; miRNA binding; protein binding; RNA binding; RNA endonuclease activity; RNA polymerase II complex binding; single-stranded RNA binding; nucleic acid binding; RNA polymerase II cis-regulatory region sequence-specific DNA binding; transcription cis-regulatory region binding
Biological process: miRNA processing; miRNA-mediated gene silencing by inhibition of translation; miRNA-mediated gene silencing by mRNA destabilization; negative regulation of angiogenesis; nuclear-transcribed mRNA catabolic process; positive regulation of transcription by RNA polymerase II; pre-miRNA processing; RISC complex assembly; siRNA-mediated gene silencing by mRNA destabilization; regulatory ncRNA-mediated post-transcriptional gene silencing; positive regulation of non-canonical NF-kappaB signal transduction; regulation of mRNA stability
Cellular component: cytoplasm; cytoplasmic ribonucleoprotein granule; RISC complex; RISC-loading complex; cytosol; nucleoplasm; nucleus; P-body
Genetic constraint (gnomAD): Loss-of-function variants: 11 observed, 110.86 expected, observed/expected ratio (o/e) 0.0992, 90% interval 0.061 to 0.16. The upper end of that interval is the gene's LOEUF score, 0.16, which puts it in group 1 of 6, group 1 being the genes least tolerant of losing a copy. Missense variants: 574 observed, 1,179.6 expected, observed/expected ratio (o/e) 0.49, 90% interval 0.45 to 0.52. Synonymous variants: 422 observed, 433.05 expected, observed/expected ratio (o/e) 0.97, 90% interval 0.9 to 1.06.
Gene-disease validity (ClinGen):
ClinGen rates the evidence that AGO1 causes each of these diseases.
complex neurodevelopmental disorder (autosomal dominant): Definitive. A disorder that involves more than one phenotype associated with the central nervous system, including but not limited to intellectual disability, autism, and seizures (epilepsy).
Homologues: Orthologues: dog AGO1 (100% identical), guinea pig AGO1 (100% identical), macaque AGO1 (100% identical), mouse Ago1 (100% identical), rabbit AGO1 (100% identical), rat Ago1 (99% identical), chimpanzee AGO1 (99% identical), tropical clawed frog ago1 (97% identical), zebrafish ago1 (96% identical), Caenorhabditis elegans alg-3 (40% identical), Caenorhabditis elegans alg-4 (40% identical), Caenorhabditis elegans ppw-2 (26% identical), and 7 more. Paralogues in human: AGO3 (85% identical), AGO4 (83% identical), AGO2 (82% identical).
Diseases named in the same sentence as AGO1 in open-access papers:
AGO1 is named in the same sentence as 74 diseases in open-access papers, as found by Europe PMC text mining. Sharing a sentence is not in itself a finding about the gene and the disease. The quoted sentences say what the papers report.
virus infection (49 papers, 2009 to 2025). "We stably introduced vector containing cDNA encoding the full-length Snail protein via viral infections into control group and Si-AGO1 cells, respectively, and the resulting cells as mass pools were subjected for in vitro analyses." (PMID 29487329, 2018). "To further gain insight into what genes AGO1-4 targets in the nucleus during viral infection, we ranked the fPAR-CLIP targets of the AGOs." (PMID 40219968, 2025). "This species-specific response likely originates from functional diversification among AGO proteins; for example, Arabidopsis AGO1 is primarily involved in the endogenous miRNA pathway, whereas N. benthamiana NbAGO2 responds more rapidly to viral infection." (PMID 41470609, 2025). "During several viral infections in A. thaliana and N. benthamiana, increased miR168 levels disrupt this homeostasis, resulting in an inhibition of AGO1-mediated antiviral RNA silencing." (PMID 39338939, 2024). "In previous works, it was found that during virus infection, the increased miR168 concentration can translationally inhibit the AGO1 expression and can also decrease the activity of antiviral silencing." (PMID 37239473, 2023). "Virus infection of various ago1 mutants can be used to investigate the interaction between VSRs and AGO1 through AGO1-IP with an α-AGO1 antibody." (PMID 36650505, 2023). "It has been found that hypoxia tolerance required AGO1 and AGO4 RNA-silencing pathways, while virus infection silenced AGO1." (PMID 35891562, 2022). "Similar increases in virus infection upon Ago1 silencing have been reported for midge-borne orthobunyaviruses in A. aegypti-derived cells, in contrast to mosquito-borne orthobunyaviruses." (PMID 35171691, 2022). "Another example of autophagy-mediated regulation and adaptation to stress by means of protein degradation is the control of the level of the protein ARGONAUTE1 (AGO1) in the context of viral infection." (PMID 34063958, 2021). "AGO18 induced by virus competes with AGO1 for binding Osa-miR168 to release miR168-mediated suppression of AGO1 upon viral infection." (PMID 37676520, 2021). "It has been reported that the induction of miR168 by virus infections negatively regulates the expression of AGO1 protein, while the accumulation of AGO1 mRNA is enhanced in parallel as a host defense reaction." (PMID 31252649, 2019). "Up-regulated miR168 by several plant virus infections mediated the host antiviral defense response by targeting AGO1." (PMID 31252649, 2019). "Until now, Arabidopsis AGO1, AGO2, AGO5, AGO7, AGO10, and rice AGO1 and AGO18 are all the AGOs reported that associate with vsiRNAs upon virus infection, reviewed in Carbonell and Carrington (2015)." (PMID 26617580, 2015). "Given that AGO1 is present in the ago18 mutant and AGO18 is present in ago1 RNAi plant and that both ago18 mutant and ago1 RNAi rice plants were very susceptible to viral infection, AGO1 and AGO18 evidently depend on each other for their antiviral activities." (PMID 25688565, 2015). "Recently, it has been reported that AGO1 is an unstable protein that is degraded by autophagy during virus infection." (PMID 25946015, 2015). "We investigated the effect of viral infection on the sorting of sRNAs onto Ago proteins and identified sRNAs derived from the human genome and incorporated exclusively into Ago1 (ASRs)." (PMID 24627180, 2014). "Argonaute 1 (AGO1) is part of the RNA-induced silencing complex (RISC) in the RNA interference pathway which can defense insects from virus infection." (PMID 25102167, 2014). "To determine the effect of viral infection on the sorting system, we compared the content of deep-sequenced RNA extracted from immunoprecipitation experiments with the Ago1 and Ago2 proteins using Epstein–Barr virus (EBV)-infected cells." (PMID 24627180, 2014). "Induction of AGO1 mRNA during viral infections is considered a plant defense response, while accumulation of miR168 is a viral counterstrategy." (PMID 24046772, 2013).
virus infection (continued). "As losing post-transcriptional repressor, accumulation of AGO1 protein is initiated, and defense of virus infection is performed mainly by AGO1vsiRNA." (PMID 24011258, 2013). "But when AGO1 is suppressed, accumulation of AGO1miR403 is lower than that under ordinary condition, consequently miR403 is down-regulated during virus infection as AGO can protect binding miRNAs." (PMID 24011258, 2013). "Viral infections in plants induce the accumulation of both the AGO1 mRNA and the miR168 mature miRNA." (PMID 24046772, 2013). "Increasing AGO1 mRNA is a recurrent plant defense reaction toward viral infections because AGO1 protein guides vsiRNAs against viral RNAs." (PMID 24046772, 2013). "Recent studies have shown that ATI family could mediate the degradation of ER-associated AGO1 (argonaute 1) protein and ER-inserted MSBP1 (membrane steroid binding protein 1), during viral infection and starvation, respectively." (PMID 40395529, 2024). "A dysregulation of the expression of genes involved in miRNA biogenesis had actually been found in several other viral infections: Dengue virus infection led to a decrease of mRNA levels of DICER, DROSHA, AGO1, and AGO2 in Huh-7 cells and this was associated with increased viral replication." (PMID 37243263, 2023). "The accumulation of AGO2 mRNA may be induced by the reduction of miR403, which depends on the suppression of the AGO1 function by virus infection." (PMID 35891562, 2022). "For instance, tombusvirus infection enhances mRNA level of AGO1 to resist virus infection, however, tombusvirus p19, as a RNA-silencing suppressor, mediates the induction of the miR168 expression to down-regulate endogenous AGO1 mRNA level and inhibit the translational capacity of AGO1 mRNA." (PMID 37676459, 2022). "In addition, localization of AGO1, another PB marker, remains unchanged upon viral infection, indicating that redistribution of XRN1-DCPs into vRC is independent of PB-related functions." (PMID 32034313, 2020). "In N. benthamiana, virus infection may regulate the expression of miR168 to alleviate the anti-viral function of AGO1 protein." (PMID 31699111, 2019). "While this suggests a general viral infection- or replication-associated induction of AGO2, similar to that of AGO1, our data revealed significant differences in the AGO2 mRNA levels at the early infection stage of 2 dpi where the replication levels of CymRSV and Cym19stop are closely comparable." (PMID 29691336, 2018). "As already outlined, viral infections generally induce the production of AGO1 mRNA." (PMID 29691336, 2018). "Both ago1 and ago2 mutants were hypersensitive to viral infection in plant." (PMID 29601523, 2018). "A plausible scenario is that at 4dpi, AGO1 might became saturated with miRNA species (loading almost strictly 5’U sRNA) preventing its onset in suppressing viral infection." (PMID 26237414, 2015). "Moreover, miR168 and its target AGO1 are both up-regulated after several virus infection even though the final outcome is less AGO1 protein by means of translational repression." (PMID 26237414, 2015). "We found that AGO1 expression was elevated by viral infection in the transgenic plants that express WT AGO18 or D833A mutant but not in those that express YF/AA, further suggesting that the small RNA binding but not slicing activity of AGO18 is required for its role in up-regulating AGO1." (PMID 25688565, 2015). "Thus, regulation of AGO1 by both host and viral factors plays a critical role in determining host responses to viral infection." (PMID 25688565, 2015). "Since AGO1 is responsible for stabilization and activity of most miRNAs, it has been well documented that miRNA levels change generally during pathogenesis, especially during virus infections, due to AGO1 targeting." (PMID 25443390, 2014).
virus infection (continued). "This difference in miR168 levels upon virus infection among dicots and monocots is important because AGO1 protein levels go down dramatically upon virus infection in Arabidopsis and Nicotiana members, while in rice, the reduction in AGO1 protein level is negligible." (PMID 25443390, 2014). "Moreover, we could recently demonstrate that the differential binding of the miRNAs modulates the expression of DCL1 and AGO1 in the early stage of a viral infection." (PMID 35563369, 2022). "On the other hand, plants could counteract this property of VSRs by a modified set of miRNAs: single mutations at specific miRNA positions, such as 7/13 or 8/12 of miR168, could provide a higher level of resistance to viral infection through the higher levels of AGO1 produced." (PMID 35563369, 2022). "To determine whether the viral-encoded RNAs are selectively sorted and if the sorting system is affected by viral infection, we compared the content of deep-sequenced RNA extracted from immunoprecipitation (IP) experiments with the Ago1 and Ago2 proteins using EBV-infected cells." (PMID 24627180, 2014). "Under these conditons, we also observed the nuclear translocation of AGO1 and AGO3 proteins upon viral infection, suggesting that the nuclear accumulation of RNAi factors is a general phenomenon during IAV infection." (PMID 40219968, 2025). "In Nicotiana benthamiana, the near-infrared light inducible TF NbPIF4 activates the transcription of RNA-DEPENDENT RNA POLYMERASE 6 (RDR6) and ARGONAUTE 1 (AGO1), thereby initiating the downstream RNAi antiviral pathway to defend against viral infection." (PMID 38396875, 2024). "The P25 (VSR) of potato virus X (PVX) interacts with Argonaute1 (AGO1) and mediates its degradation through the 26S proteasome, thereby suppressing the antiviral RNA silencing and accelerating virus infection." (PMID 37628763, 2023). "The SCF complex is the best studied of the E3 Ub-ligases in plants, and is thus far identified in the turnover of AGO1, NLR gene mediated anti-virus innate immunity as well as the direct regulation of plant virus infection." (PMID 27869775, 2016). "We have previously shown that rice AGO1 as well as AGO18, a member of a new AGO clade that is conserved in monocots, is highly induced by viral infection." (PMID 25688565, 2015). "Surprisingly, a lower expression level of vvi-miR168, which translationally regulates Argonaute 1 (AGO1) expression in A. thaliana and N. benthamiana, was induced by virus infection." (PMID 23596440, 2013). "This indicates that P0 protein does not prevent siRNA generation nor their loading on AGO1 in the viral infection context." (PMID 30405546, 2018). "To analyze the vsiRNA generated during viral infection and potentially loaded on AGO1 we agroinoculated A. thaliana plants expressing or not a functional epitope-tagged version of AGO1 [FLAG-AGO1;] with wild-type TuYV (TuWT)." (PMID 30405546, 2018). "A 2.5-fold increase in transcription of AGO1 was observed also in self-grafted Sl-Me over its non-grafted counterpart, meaning that in this genotype the AGO1 overexpression was due to the graft itself rather than to a response to viral infection." (PMID 26496695, 2015). "Excluding from the analysis enzymes that were upregulated in leaves and/or roots of the self-grafted genotypes, we can conclude that the overexpression of AGO1, AGO4 and DCL2 in the leaves of Sl-UC grafted on Sl-Ma was very likely in response to viral infection." (PMID 26496695, 2015). "In any case, though AGO1 has been noted as a chief actor in antiviral silencing, other AGOs significantly contribute to the antiviral response, and indiscriminate AGO targeting by P0 may well be advantageous for the success of viral infection." (PMID 36552310, 2022). "This may be the case for rice, where neither a strong induction of miR168, nor a corresponding reduction in AGO1 levels has been observed upon viral infections." (PMID 25443390, 2014).
virus infection (continued). "Finally, in the eluates of AGO1 immunoprecipitations miR159 was detected in both the mock and SPMMV-infected N. benthamiana plants, indicating that miRNAs were associated with AGO1 regardless of virus infection (lanes 1, 2 and 4, 5)." (PMID 33925878, 2021). "During virus infection, the decrease in the translation of AGO1 protein leads to accumulation of AGO2, due to the absence of AGO1-miR403-mediated posttranscriptional down-regulation of AGO2." (PMID 27711201, 2016).